MIR936 (microRNA 936)
Synonyms: hsa-mir-936; MIRN936
Gene: MicroRNA gene on chromosome 10 (104,048,089 to 104,048,186, reverse strand). Ensembl gene ENSG00000283788.
Gene Ontology:
Biological process: miRNA-mediated post-transcriptional gene silencing
Cellular component: RISC complex
Homologues: Orthologues: chimpanzee ptr-mir-936 (100% identical).